PDPN (podoplanin)
Diseases named in the same sentence as PDPN in open-access papers (continued):
Sharing a sentence is not in itself a finding about the gene and the disease.
tumor (continued). "For example, the glycoprotein podoplanin (PDPN) expressed on the surface of many tumor cells binds the C-type lectin receptor-2 (CLEC-2) on the platelets leading to platelet aggregation and thrombus formation." (PMID 37520562, 2023). "In particular, PDPN is involved in tumour cell growth, invasion, migration, metastasis and inflammation." (PMID 36156321, 2023). "The enhanced immunoexpression of PDPN signifies that this immunomarker can have a role in tumor cell differentiation and the neoplastic progression of OSCCs." (PMID 37273383, 2023). "PDPN expression in early invasive OSCCs is heterogeneous and fragmented, often confined to the invasive tumor front areas." (PMID 37273383, 2023). "No positive correlations were observed for ACTA2, COL11A1, TNC, and PDPN genes in PanCK(-) AOIs at EOCC tumor center or at LOCC tumor invasive margin." (PMID 37964075, 2023). "Annexin V-FITC was used to identify and quantify apoptotic cells, and pEMT tumor cells were detected using podoplanin antibody." (PMID 38137525, 2023). "PDPN has been associated with tumor cell migration and proliferation in vitro, but the tumor progression in a preclinical mouse model occurs independently of PDPN." (PMID 36434176, 2023). "Consistently, we found that the expression of PDPN in GC cells activated CAFs and promoted the secretion of tumour‐promoting cytokines in CAFs." (PMID 36156321, 2023). "PDPN is a component of tumor EVs that reprograms EV biogenesis and release and modulates lymphatic vessel formation." (PMID 36671802, 2023). "Consistently, the CAF/PDPN-OE group had significantly increased tumor volume and weight compared with the CAF/PDPN-Mock group." (PMID 37993428, 2023). "For example, they showed that the myofibroblast-like cells closest to the tumour exhibited signs of oxygen deprivation; they also produced podoplanin, a protein known to promote cancer progression." (PMID 37350578, 2023). "When U87 cells were co-cultured with induced THP1 cells for 72 h, we found that the siPDPN group had slow proliferation, indicating that PDPN knockdown affected the mutual benefit between tumor cells and macrophages." (PMID 36434176, 2023). "In the present study, within different grades of OSCC, the location of PDPN expression was predominantly evident in the entire tumor islands as the grade of OSCC increased." (PMID 37273383, 2023). "The expression of MPM markers was analyzed using IHC and positive tumor cells were quantified: all tumors were positive for Calretinin, Mesothelin, and Podoplanin, with an average of positive tumor cells/sample of 79%, 87%, and 61%, respectively." (PMID 37345150, 2023). "The PDPN extracellular domain has tandem platelet aggregation-stimulating domains, such as PLAG1, PLAG2, and PLAG3, which are associated with tumor-induced platelet aggregation." (PMID 37894446, 2023). "Accordingly, podoplanin-expressing CAFs create a supportive microenvironment that promotes tumor progression." (PMID 36376711, 2023). "Flow cytometry of tumor mases in the omentum showed an increased presence of CAFs (PDPN+/CD31−/CD45−/RFP−) in KPC-HAPLN1 tumor-bearing mice, which was confirmed by immunofluorescence analysis." (PMID 37095087, 2023). "Platelets express the C-type lectin-like receptor 2 (CLEC-2) that enables binding to podoplanin (PDPN)-expressing tumor cells and, thereby, promote metastatic spread." (PMID 38067218, 2023). "PDPN+ CAFs exert tumor-promoting functions by facilitating the invasion of cancer cells, remodeling of the ECM, and promoting an immunosuppressive microenvironment." (PMID 37143134, 2023). "PDPN induces both plasma membrane extension and the actin cytoskeleton rearrangement which favors tumor cell motility." (PMID 37273383, 2023). "PDPN expression is observed not only in tumor cells but also in the tumor stroma, which includes CAFs." (PMID 35159384, 2022).
tumor (continued). "In malignant tumors, CLEC-2 and podoplanin work together to activate platelets to promote tumor metastasis and promote tumor-related thrombosis." (PMID 35902826, 2022). "Taken together, these results indicate that nontransformed cells form cadherin junctions with adjacent transformed cells to stabilize p120-catenin expression and decrease PDPN expression in order to inhibit tumor cell proliferation." (PMID 35177067, 2022). "Podoplanin expression of tumor cells was quantified based on the estimated percentage of positively stainedtumor cells." (PMID 36247509, 2022). "Significant relationships between tumor podoplanin and tumor MMP-13 were consistent with previous findings linking MMP-13 overexpression to advanced staging and lymph node metastases." (PMID 36505148, 2022). "As expected, PDPN was highly expressed in cytoplasmic areas of tumor cells, correlating with high histological grading." (PMID 36077194, 2022). "Most of the tumors studied, showed podoplanin expression restricted to the peripheral layer of tumor nests." (PMID 36247509, 2022). "Another important marker expressed in several tumor cells and CAFs is podoplanin, which is a transmembrane glycoprotein and has a role in cell migration and invasion through the protrusion of the cell membrane." (PMID 36362726, 2022). "The results of the current study support the importance of double staining (Ki-67/podoplanin) in determining tumor lymphangiogenesis, increasing the accuracy of diagnosis and prognosis for the patients with HNSCC." (PMID 36077194, 2022). "Platelets have an important impact on the occurrence, development, and prognosis of tumors and can promote the direct interaction between aggrus/podoplanin and clec-2 to promote tumor growth and metastasis." (PMID 35928880, 2022). "Our study demonstrates that high podoplanin expression predicts lymph node metastasis and aggressive tumor behavior." (PMID 36247509, 2022). "Elevated PDPN expression in CAFs from lung, breast, and pancreatic tumors is correlated with tumor malignancy and poor prognosis." (PMID 35159384, 2022). "In the tumor microenvironment, CCL21 acts as a potent chemoattractant for CCR7-positive tumor cells by binding to podoplanin on cancer-associated fibroblasts (CAFs), thereby promoting the stromal invasion of cancer cells." (PMID 35163233, 2022). "Inhibition of PDPN-mediated tumor progression by regulating CD44 glycosylation deserves further in-depth research." (PMID 35936713, 2022). "Congruently, lymphatic-specific podoplanin deletion led to a decrease in medullary sinus macrophages in tumor-draining LNs in vivo." (PMID 35892863, 2022). "Most studies have suggested that tumor podoplanin expression correlates positively with aggressive tumor behaviors such as lymph node metastasis, local aggression, and survival rate." (PMID 35163233, 2022). "Podoplanin-expressing tumor cells have promoted hematogenous metastasis through the CLEC-2-induced platelet aggregation." (PMID 35936717, 2022). "The Src tyrosine kinase phosphorylates effector proteins to induce expression of the podoplanin (PDPN) receptor in order to promote tumor progression." (PMID 35177067, 2022). "Most of these genes were tumor cell metastasis-associated genes such as TNC, PLAU, PDPN, SPARC, LUM, and especially SNAI2 (Zinc finger protein SLUG transcription factor)." (PMID 35742914, 2022). "The abundance of podoplanin is related to the immune evasion environment characterized by the infiltration of tumor macrophages and dysfunctional CD8+ T cells." (PMID 35902826, 2022). "This raises safety concerns regarding PDPN-targeting therapies and necessitates the development of a better approach to specifically target cancer cells to overcome the on-target-off-tumor effect." (PMID 35991754, 2022). "The distribution of the PDPN-positive cell region was more localized to the peripheral area of the tumor nests than that of CD44- and P63-positive cell regions." (PMID 35159384, 2022).
tumor (continued). "CLEC-2 and podoplanin-expressing tumour cells interact to increase angiogenesis, tumour development, and metastasis." (PMID 35082906, 2022). "In conclusion, our data suggest that lymphatic podoplanin acts as a macrophage adhesion receptor to maintain or expand sinusoidal macrophages in tumor-draining LNs." (PMID 35892863, 2022). "PDPN-expressing macrophages (PoMEs) have been validated to promote tumor lymphangiogenesis and LNM in BRCA." (PMID 35847584, 2022). "PDPN is known to contribute to tumor progression by inducing cancer cell migration and tumor invasion connected to the EMT mechanism (145146) and in the absence of EMT markers." (PMID 35814405, 2022). "In our integrated analysis of human colon mucosa and tumor fibroblasts, PDPN was prominently expressing in CXCL14+INHBA+ fibroblasts." (PMID 36463319, 2022). "A mouse-human chimeric mAb (chLpMab-2 and chLpMab-23; human IgG1) exhibited high ADCC activity against PDPN-expressing cells and abolished tumor growth in xenograft models." (PMID 35159384, 2022). "Podoplanin (PDPN) is a cell-surface mucin-like glycoprotein that plays a critical role in tumor development and normal development of the lung, kidney, and lymphatic vascular systems." (PMID 35159384, 2022). "A circulating tumor cell chip composed of podoplanin antibody has been used to capture malignant pleural mesothelioma cells in preclinical models." (PMID 36005042, 2022). "We assessed PDPN expression in tumor cells, the presence, morphology and density of lymphatic vessels, and the existence of lymphovascular lesions with tumor invasion." (PMID 36077194, 2022). "As for PDPN immunoexpressing in tumors, high reactivity was present at the periphery of most tumor areas." (PMID 36077194, 2022). "The peripheral layers of tumor showed increased expression of podoplanin because they have a higher proliferative capacity and the central tumor cells lack podoplanin expression as they are terminally differentiated cells." (PMID 36247509, 2022). "When pro-inflammatory cells interpreted cytokine-mediated signal transduction in SCC cells, podoplanin expression reduces and with it tumor invasion." (PMID 36247509, 2022). "It has been shown that podoplanin-positive CAFs in the tumor microenvironment confer a worse prognosis because of the higher risk of lymph node metastasis and tumor progression." (PMID 36362726, 2022). "Although elevated levels of PDPN have been correlated with increased malignancy in different tumorsits relevance for tumor progression is still unclear." (PMID 35814405, 2022). "The PDPN-positive population exhibited clonal expansion ability and tumor formation in mice—characteristics of CSCs, which were initially observed in A431 SCC cells." (PMID 35159384, 2022). "Podoplanin has been reported to contribute to cancer pathogenesis by promoting tumor cell invasion and spreading." (PMID 35902826, 2022). "Intratumoral injection of ex-vivo isolated lymph node podoplanin+ cells, which consists of follicular reticular cells and LECs, promotes tumor growth through the inhibition of tumor-infiltrating CD4+ T lymphocytes." (PMID 35216243, 2022). "Immunoreactivity for Ki-67 was limited to the nucleus in all samples, and PDPN staining was present in different intensities in cytoplasmic tumor cells." (PMID 36077194, 2022). "We found that PDPN expression is highly correlated with tumor grade (grade II, n=213; grade III, n=239; grade IV, n=149; p<0.0001)." (PMID 36059614, 2022). "Podoplanin is a transmembrane mucin-like glycoprotein expressed in various types of cancers and influences tumor cell migration and metastasis." (PMID 36005042, 2022). "Some drugs, such as 5-nitrobenzoate-2CP, inhibit the podoplanin-CLEC-2 union, which causes the inhibition of tumor cell-induced platelet aggregation (TCIPA) and the consequent prevention of tumor metastasis without the risk of hemorrhage." (PMID 35207103, 2022).
tumor (continued). "In contrast, EBP1 knockdown inhibited PDPN transcription, invasiveness, and tumor formation in immunodeficient mice." (PMID 35159384, 2022). "In the immunohistochemical staining of lung SCC tissue, PDPN is mainly localized at the periphery of invading tumor nests with CD44 and P63." (PMID 35159384, 2022). "On the other hand, LMVD has been highly correlated with podoplanin expression in tumor cells (p = 0.007), supporting the important role of podoplanin in the progression, invasion, and metastasis of head and neck tumors." (PMID 36077194, 2022). "Here, we isolated CD31+ podoplanin+ LN LECs and devised the transcriptional responses of individual cells to primary tumor growth." (PMID 35892863, 2022). "Interaction with ERM family proteins is essential for PDPN-mediated epithelial-to-mesenchymal transitions (EMTs) in tumor development, as well as lymphangiogenesis and the immune response." (PMID 35159384, 2022). "In the pathological tumor section, PDPN-expressing tumor cells have been observed sometimes at the invasive front, where CD45-positive inflammatory cells infiltrate." (PMID 35159384, 2022). "Clustering of podoplanin by platelet CLEC-2 regulates several molecular pathways involved in tumor cell migration and invasion." (PMID 35902826, 2022). "This knowledge was exploited to study the role of PDPN+ CAFs under the influence of hypoxia in tumour progression." (PMID 35355992, 2022). "Despite the significant reduction in LRRC15+ cells in Dptki/kiTgfbr2fl/fl tumours, the total number of PDPN+CD31– fibroblasts was unchanged between both groups, which indicated that a compensation mechanism occurred to maintain the CAF compartment." (PMID 36171287, 2022). "Tumor cells can also express binding proteins (such as podoplanin, PDPN) which can bind to platelet surface adhesion proteins (such as C-type lectin-like receptor 2, CLEC-2) to promote platelet activation." (PMID 35659308, 2022). "One study found that podoplanin expression in colonic CAFs had a better prognosis and podoplanin knockdown in transwell assays enhanced tumor cell invasiveness." (PMID 35936717, 2022). "LRRC15+ and LRRC15– CAFs from DTR– tumours or PDPN+ LRRC15-depleted CAFs from DTR+ tumours were sorted 12 days after DT treatment." (PMID 36171287, 2022). "The study reported PDPN overexpression due to hypoxia in fact favoured invasion of CCR7+ tumour cell into CCL21+ peripheral lymph nodes leading to metastasis." (PMID 35355992, 2022). "They react to podoplanin by targeting the oncofetal M2A antigen, resulting in the membranous expression of tumor cells." (PMID 36247509, 2022). "Podoplanin is expressed in tumor cells or peritumoral cells and its expression correlates with tumor progression and prognosis in several malignancies of the skin and other organs, including glioblastomas and SCC of the esophagus, head, and neck." (PMID 35163233, 2022). "As a result, Dptki/kiTgfbr2fl/fl tumours had a significant reduction in the total number of LRRC15+PDPN+ CAFs compared with control Dptwt/wtTgfbr2fl/fl tumours, which indicatedthat LRRC15+ cells depend on TGFβR2 signalling in DPT+ cells for their formation." (PMID 36171287, 2022). "In turn, TGFβR2 expression on PDPN+ CAFs from Dptki/kiTgfbr2fl/fl tumours was reduced by about 90% compared with Dptwt/wtTgfbr2fl/fl tumours." (PMID 36171287, 2022). "Studies have emphasised that podoplanin has a potential role for tumor progression and lymphovascular invasion." (PMID 36247509, 2022). "Regarding podoplanin as a biomarker for tumor cell migration, our findings suggest a more meaningful association between ENE and podoplanin activity, especially in terms of the invasive front." (PMID 35256682, 2022). "In xenograft tumorigenesis experiments, we discovered that PDPN expression greatly influences tumor growth." (PMID 36059614, 2022). "A potential role of podoplanin in cancer progression was suggested due to its expression in various tumor model experiments, both in vitro and in vivo." (PMID 36247509, 2022).
tumor (continued). "CLEC-2 on platelets binding with podoplanin on tumor cells can induce platelet release of TGF-β and promote EMT." (PMID 35936717, 2022). "PDPN induces tumor invasion by mediating single-cell migration following EMT or collective cell migration in the absence of EMT." (PMID 36428690, 2022). "Nontransformed cells form cadherin junctions with adjacent transformed cells to decrease PDPN expression in order to inhibit tumor cell proliferation." (PMID 35177067, 2022). "Angiogenesis, tumour growth, and metastasis are all aided by CLEC-2 and podoplanin-expressing tumour cells interaction." (PMID 35082906, 2022). "Our groups previously established NZ-1 series (NZ-1, NZ-1.2, NZ-1.3, or NC-08) among anti-PDPN mAbs, which have also been employed for tumor diagnosis by means of immunohistochemistry." (PMID 35159384, 2022). "Tissue analysis in 14 types of cancer suggested that podoplanin expression in the tumor stroma is an indication of cancer spread and that expression of podoplanin in cancer cells indicates strong tumor aggressiveness." (PMID 35256682, 2022). "Nontransformed cells form cadherin junctions with neighboring transformed cells to inhibit tumor cell growth, and PDPN can override this form of growth control." (PMID 35177067, 2022). "In our case, an increased Ki-67 proliferation index was present in 82% of the tumor areas, and there was a statistical correlation between it and histological grading (p = 0.050) and with PDPN expression (p = 0.028)." (PMID 36077194, 2022). "Src phosphorylates the p130Cas/BCAR1 adaptor protein to induce PDPN expression in order to promote tumor cell expansion, and contact inhibition reverses this process." (PMID 35177067, 2022). "The primary markers for liquid biopsy are the transmembrane receptor glycoprotein podoplanin, circulating tumor DNA, and exosomes." (PMID 36005042, 2022). "Podoplanin (D2-40), a marker of lymphatic lineage, is more frequently expressed in Dabska tumor than RH." (PMID 33593408, 2021). "Microscopic analysis of B16F10 tumors growing in Cxcl13-Cre/tdTomato EYFP mice revealed that lineage-traced EYFP+ cells localized mainly in the tumor margin co-express PDPN both in PBS- and artLCMV-treated tumors (arrowheads)." (PMID 34354077, 2021). "Human CCA arrays were co-stained with Podoplanin and CK19 and high degree of tumor associated lymphangiogenesis was observed." (PMID 34831316, 2021). "These investigations suggest that mAbs neutralizing either CLEC2 or PDPN specifically inhibit platelet-tumor interaction and tumor metastasis." (PMID 34987523, 2021). "Some EMT factors in IF region which are effective in tumorigenesis and invasion processes, include collagen type IV, Laminin, Fibronectin, MMPs, miRNA, Oncofetal antigens, Podoplanin and also Glucose-transporter-1 that saves tumor cells from hypoxia." (PMID 34306128, 2021). "Overall, these data suggest that PDPN confers cancer cells survival benefits, promoting tumor growth, invasion, and metastasis." (PMID 34987523, 2021). "The novel anti-PDPN antibody NZ-16 has a higher binding affinity and higher tumor uptake compared with the previous antibody NZ-12." (PMID 34685483, 2021). "Taken together, PDPN is considered as a ‘pinpoint’ that interconnects between tumor and platelets, regulating VTE as well as tumor progression." (PMID 34987523, 2021). "It has been shown that PDPN regulates stem cells in normal and tumor tissues, and also reported as a valuable biomarker for cancer risk assessment of malignant transformation in oral leukoplakia." (PMID 34201050, 2021). "In the xenograft mouse model, PDPN-overexpressing OSCC cells promoted tumor growth and intratumoral platelet accumulation, implying that PDPN mediates TCIPA formation in OSCC." (PMID 34987523, 2021).